PANX1 (pannexin 1)
Description:
Ion channel involved in a variety of physiological functions such as blood pressure regulation, apoptotic cell clearance and oogenesis. Forms anion-selective channels with relatively low conductance and an order of permeabilities: nitrate>iodide>chlroride>>aspartate=glutamate=gluconate (By similarity). Can release ATP upon activation through phosphorylation or cleavage at C-terminus. May play a role as a Ca(2+)- leak channel to regulate ER Ca(2+) homeostasis. [Caspase-activated pannexin-1]: During apoptosis, the C terminal tail is cleaved by caspases, which opens the main pore acting as a large-pore ATP efflux channel with a broad distribution, which allows the regulated release of molecules and ions smaller than 1 kDa, such as nucleotides ATP and UTP, and selective plasma membrane permeability to attract phagocytes that engulf the dying cells.
Synonyms: MRS1; UNQ2529; PX1; OOMD7; OZEMA7
Tractability: Small molecule: a structure with a bound ligand is known. Antibody: UniProt places it where antibodies can reach, with high confidence; its Gene Ontology location is reachable by antibodies, with high confidence; UniProt predicts a signal peptide or a membrane-spanning region; the Human Protein Atlas places it where antibodies can reach. PROTAC: ubiquitination databases record sites on it; its protein half-life has been measured.
Target class: Ion channel; Other ion channel
Gene: Protein-coding gene on chromosome 11 (94,128,828 to 94,181,968, forward strand). Ensembl gene ENSG00000110218.
Subcellular location: Cell membrane; Endoplasmic reticulum membrane
Subcellular location (Human Protein Atlas): Plasma membrane
Pathways (Reactome):
Cellular responses to stimuli: High laminar flow shear stress activates signaling by PIEZO1 and PECAM1:CDH5:KDR in endothelial cells; Mechanical load activates signaling by PIEZO1 and integrins in osteocytes
Immune System: The NLRP3 inflammasome
Neuronal System: Electric Transmission Across Gap Junctions
Gene Ontology:
Molecular function: ATP transmembrane transporter activity; calcium channel activity; leak channel activity; protein binding; signaling receptor binding; gap junction hemi-channel activity; monoatomic anion channel activity; structural molecule activity; wide pore channel activity; actin binding; actin filament binding; channel activity; gap junction channel activity; protease binding; protein-containing complex binding; scaffold protein binding; transmembrane transporter binding
Biological process: ATP transport; calcium ion transport; monoatomic cation transport; positive regulation of interleukin-1 beta production; cell-cell signaling; monoatomic anion transmembrane transport; calcium ion transmembrane transport; positive regulation of interleukin-1 production
Cellular component: bleb; endoplasmic reticulum; endoplasmic reticulum membrane; gap junction; membrane; plasma membrane; protein-containing complex
Genetic constraint (gnomAD): Loss-of-function variants: 25 observed, 35.52 expected, observed/expected ratio (o/e) 0.7, 90% interval 0.51 to 0.98. The upper end of that interval is the gene's LOEUF score, 0.98, which puts it in group 4 of 6, group 1 being the genes least tolerant of losing a copy. Missense variants: 508 observed, 505.83 expected, observed/expected ratio (o/e) 1, 90% interval 0.93 to 1.08. Synonymous variants: 222 observed, 210.28 expected, observed/expected ratio (o/e) 1.06, 90% interval 0.94 to 1.18.
Homologues: Orthologues: chimpanzee PANX1 (99% identical), guinea pig PANX1 (90% identical), rat Panx1 (88% identical), mouse Panx1 (86% identical), rabbit PANX1 (86% identical), dog PANX1 (85% identical), pig PANX1 (84% identical), macaque PANX1 (81% identical), tropical clawed frog panx1 (65% identical), zebrafish panx1a (55% identical), zebrafish panx1b (53% identical). Paralogues in human: PANX3 (37% identical), PANX2 (26% identical).
Diseases named in the same sentence as PANX1 in open-access papers:
PANX1 is named in the same sentence as 228 diseases in open-access papers, as found by Europe PMC text mining. Sharing a sentence is not in itself a finding about the gene and the disease. The quoted sentences say what the papers report.
breast carcinoma (37 papers, 2014 to 2025). "PANX1 expression was also positively correlated with tumor-associated neutrophil (TAN) infiltration in breast cancer TME and TANs highly expressed ENTPD1 (CD39)/NT5E (CD73)." (PMID 35884429, 2022). "PANX1 expression was also positively correlated with tumor-associated neutrophil (TAN) infiltration in breast cancer TME, and TANs highly expressed CD39/CD73, which synergistically build a high exADO immunosuppressive TME and promote tumor progression." (PMID 35884429, 2022). "A somatic nonsense mutation, Q89*, encoding a truncated form of PANX1 protein, was similarly shown to be enriched in highly metastatic breast cancer cells." (PMID 34796785, 2021). "Of note, both PANX1 and β-catenin have been implicated in survival of metastatic breast cancer cells and poor patient outcome." (PMID 33647315, 2021). "Our results suggest PANX1 overexpression in breast cancer is associated with a shift towards an EMT phenotype, in silico and in vitro, attributing to it a tumor-promoting effect, with poorer clinical outcomes in breast cancer patients." (PMID 31817827, 2019). "Recently, Panx1 was shown to be mutated in metastatic breast cancer cell lines, leading to increased ATP-channel activity and promotion of breast cancer cell survival during extravasation." (PMID 27099931, 2016). "Whole-transcriptome RNA sequencing of in vivo-selected highly metastatic sub-lines of human breast cancer cells revealed an activating mutation in the ATP release channel pannexin-1 (PANX11−98)." (PMID 27618016, 2016). "In addition, PANX1 overexpression is associated with the EMT transformation of breast cancer cells and poorer clinical outcomes in breast cancer patients." (PMID 36601599, 2022). "Interestingly, a mutant truncated PANX1 channel (PANX11–89) has also been associated with highly metastatic breast cancer cells." (PMID 32656213, 2020). "Furthermore, a mutation encoding a truncated form of PANX1 is recurrently enriched in highly metastatic breast cancer cells." (PMID 30459312, 2018). "A recent RNASeq analysis of breast cancer cells with different metastatic capacities revealed that cell lines with high metastatic potential had significantly enriched mutant mRNA encoding a N-terminal truncated PANX1 channel." (PMID 29865195, 2018). "Moreover, an US Food and Drug Administration (FDA)-approved anti-parasitic drug, Ivermectin allosterically regulates P2X4 receptors in breast cancer cells through opening of the P2X4/P2X7-gated Panx1 channels, which is associated with ATP release and consequently, cancer cell death." (PMID 29865195, 2018). "Some channels such as the neonatal splice variant of Nav1.5 (nNav1.5) in, e.g., primary breast cancer cells, or mutated PANX1 (PANX11−98) in circulating cancer cells, seem to be highly cancer cell-associated and might be used to specifically target cancer cells in the future." (PMID 27618016, 2016). "Intriguingly, metastatic breast cancer cells evolved survival strategies through Panx1 truncation mutants (1-89aa), which exhibited force-dependent ATP efflux." (PMID 40909173, 2025). "Metastatic breast cancer cells with a PANX1 channel-activating mutation gained a survival advantage due to an increase in the release of ATP, which was modulated via PANX1 when the breast cancer cells became lodged in the microvasculature." (PMID 41477487, 2025). "In breast cancer, Panx1 has been shown to be highly expressed in metastatic foci and is associated with an enhanced epithelial-mesenchymal transition (EMT)." (PMID 40978734, 2025). "Because PANX1 is upregulated in most other cancer types in which it has been reported, including melanoma, breast cancer and leukemia, it seems more likely that PANX1 is increased in cSCC compared to normal tissue." (PMID 39560179, 2025). "Some studies have indicated that drugs like ivermectin can activate Panx1 and induce cancer cell death, as observed in breast carcinoma." (PMID 40227837, 2025).
breast carcinoma (continued). "PANX1 has been revealed to promote metastasis in a variety of tumors including hepatocellular carcinoma, testicular cell carcinoma, and breast cancer." (PMID 38743344, 2024). "Panx1 expression positively correlates with the occurrence or progression of melanoma, hepatocellular carcinoma, breast cancer, colorectal cancer, and hematologic malignancies." (PMID 36833374, 2023). "In highly metastatic breast cancer cell lines, the membrane stretches endured in microcirculation induce ATP release from mechanosensitive PANX1 channels." (PMID 36750864, 2023). "Reportedly, apoptotic breast cancer cells secreted spermidine to foster NET formation in a pannexin 1 (Panx1) channel-dependent manner, which attenuated antitumor immunity." (PMID 38283351, 2023). "In breast cancer cells, in which PANX1 over-expression is correlated with poorer overall survival, the expression of genes involved in the EMT pathway correlated positively with PANX1 expression." (PMID 37056395, 2023). "This study suggests that high PANX1 expression is associated with high TAN infiltration and adenosine production to induce local immunosuppression in basal-like breast cancer TME." (PMID 35884429, 2022). "PANX1 expression was positively correlated with exATP and exADO levels in basal-like breast cancer TME." (PMID 35884429, 2022). "In summary, the expression of PANX1 was positively correlated with TANs infiltration through exATP secretion in basal-like breast cancer." (PMID 35884429, 2022). "Our study demonstrated that ENTPD1 and NT5E expressions were higher in the PANX1 high expression basal-like breast cancer and PANX1 upregulated exADO levels in the TME." (PMID 35884429, 2022). "Using CIBERSORT LM22, we analyzed the effect of PANX1 expression on basal-like breast cancer immune microenvironment in TCGA-BRCA (n = 186) data and GSE103091(n = 238) dataset." (PMID 35884429, 2022). "The results revealed that PANX1 acted as a poor prognostic factor for breast cancer and had high expression in basal-like breast cancer." (PMID 35884429, 2022). "The effects of different structures and different activation levels of PANX1 on the state of the breast cancer TME deserve further investigation." (PMID 35884429, 2022). "Increased Panx1 has been reported in several conditions, such as cerebral ischemia, in metastatic cell lines of patients with breast cancer, in Crohn’s disease and in ulcerative colitis." (PMID 36072579, 2022). "Third, we mainly focused on the effect of PANX1 expression levels on breast cancer TME in this study." (PMID 35884429, 2022). "We found that the TANs infiltration was significantly higher in PANX1 high expression basal-like breast cancer and that the genes coexpressed with PANX1 were related to granulocyte migration and neutrophil activation." (PMID 35884429, 2022). "This study revealed that basal-like breast cancer tissues had high PANX1 expression, which was positively correlated with tumor-associated neutrophils (TANs) and the accumulation of exADO, forming an immunosuppressive TME." (PMID 35884429, 2022). "The results revealed that basal-like breast cancer with high PANX1 expression (n = 6) had more infiltrating TANs than basal-like breast cancer with low PANX1 expression (n = 6) and Luminal subtype (n = 3) (p < 0.05 for TIMER and quanTIseq method)." (PMID 35884429, 2022). "This correlation between ETV4 and PANX1 levels also remains in breast cancer, prostate cancer, and melanoma, which further broadens the contextual implications of ETV4 for PANX1 expression." (PMID 35194046, 2022). "In this study, we performed RNA sequencing, bioinformatics analysis, surgical specimen histological validation, and exATP/extracellular adenosine (exADO) assays to reveal the role of PANX1 in regulating the immune microenvironment of basal-like breast cancer." (PMID 35884429, 2022).
breast carcinoma (continued). "Previous studies have reported that PANX1 promotes cell proliferation and tumorigenic properties in melanoma cells, testicular cancer, and breast cancer." (PMID 34796785, 2021). "Significantly higher PANX1 mRNA levels were seen in all of the intrinsic breast cancer subtypes when compared to normal breast cancer tissues of the TCGA data set." (PMID 31817827, 2019). "PANX1 expression has been reported during mouse mammary gland development and in the adult mouse mammary gland; however, its role in breast cancer is still evolving." (PMID 31817827, 2019). "Overall, pharmacological or genetic downregulation of PANX1 in breast cancer cells reverses the already existing EMT, i.e., promote a MET state in those cells." (PMID 31817827, 2019). "In fact, PANX1 was elevated in the different breast cancer subtypes not only at the transcriptional levels but also at the protein levels, as determined by Proteomics analysis of PANX1 protein levels in the intrinsic breast cancer subtypes." (PMID 31817827, 2019). "Here we report elevated expression of PANX1 in different breast cancer (BRCA) subtypes using RNA-seq data from The Cancer Genome Atlas (TCGA)." (PMID 31817827, 2019). "We provide evidence that PANX1 upregulation is correlated with poor prognosis in breast cancer patients and that it is differentially expressed in the different “intrinsic” human breast cancer subtypes." (PMID 31817827, 2019). "To investigate the role that PANX1 plays during cancer progression, we compared PANX1 expression between primary breast carcinoma (BRCA) using the RNA-seq dataset obtained from The Cancer Genome Atlas (TCGA)." (PMID 31817827, 2019). "Reversal of EMT upon PBN treatment prompted us to assess the effect of functional inhibition of PANX1 channels on the metastatic potential of breast cancer cells." (PMID 31817827, 2019). "Remarkably, PANX1 was of prognostic value in a microarray dataset from the Molecular Taxonomy of Breast Cancer International Consortium (METABRIC) (intermediate vs. low: HR = 1.4, p = 0.012; high vs. low: HR = 1.89, p < 0.001)." (PMID 31817827, 2019). "Using qRT-PCR, we also investigated the expression of PANX1 in primary breast cancer tissues from a local cohort of archived breast cancer patients’ samples." (PMID 31817827, 2019). "We assessed the effect of PANX1 channel on breast cancer progression via pharmacological inhibition of PANX1 in these cells." (PMID 31817827, 2019). "Together, our findings identify a role for PANX1 in breast cancer progression and that PANX1 mediates this tumor-promoting role by modification of the EMT pathway." (PMID 31817827, 2019). "In this pathway, upregulated PANX1 enhances breast cancer cells EMT phenotype, the enhanced EMT phenotype enhances breast cancer cells metastatic potential and invasiveness, for example by increasing the levels or activity of MMPs and other metastatic genes." (PMID 31817827, 2019). "This study supports a role for PANX1 in cancer progression and metastasis, where its expression is upregulated in all breast cancer subtypes and upregulated PANX1 levels in breast cancer tissues are correlated with poor clinical outcomes." (PMID 31817827, 2019). "On the other hand, high PANX1 mRNA expression is correlated with poor overall survival in breast cancer patients." (PMID 30459312, 2018). "In this study, Panx1 was found to be expressed in many breast cancer cell lines, and a truncated mutant form of Panx1 was particularly enriched in highly metastatic breast cancer lines like CN-LM1A and MDA-LM2." (PMID 27229305, 2016). "All analyzed breast cancer cells depicted similar expression levels of PANX1 and ABCC1 whereas a considerable variability of ANKH and SLC22A11 expression was observed." (PMID 25496233, 2014). "In addition, extra reports suggest that Panx1 is highly expressed in breast cancer, colon cancer, and cSCC, and is associated with poor prognosis in patients." (PMID 40909173, 2025).
breast carcinoma (continued). "Panx1 has also been correlated with poor prognosis in breast cancer." (PMID 40227837, 2025). "In the metastatic breast cancer line, it was found that the truncated Panx11_89 protein acted as an activator of Panx1, inducing ATP release from cells and promoting breast cancer cell survival during traumatic intravascular deformation through purinergic receptors P2Y." (PMID 40227837, 2025). "It was reported that PANX1 had certain effect on the prognosis and metastasis of various tumor, such as pro-carcinogenic effects in pancreatic adenocarcinoma, breast cancer, hepatocellular carcinoma, testicular carcinoma, melanoma, and anticarcinogenic effects in rhabdomyosarcoma." (PMID 35884429, 2022). "In this study, we investigated the effect of PANX1 in basal-like breast cancer primary lesions." (PMID 35884429, 2022). "Previous FRAP studies performed at room temperature on GFP-tagged mouse Panx1 expressed in a breast cancer cell line (BICR-MIRk) and zebrafish Panx1a expressed in N2a cells revealed diffusion kinetics comparable to those reported here, with recovery of 45–60% at one min after bleaching." (PMID 36291086, 2022). "This study suggested that PANX1 was highly expressed in basal-like breast cancer and might be a poor prognostic factor." (PMID 35884429, 2022). "We found that PANX1 was highly expressed in basal-like breast cancer and could increase the exATP level in the TME and that high PANX1 expression was associated with poor prognosis in basal-like breast cancer." (PMID 35884429, 2022). "PANX1 and MPO expression was positive correlated, indicating that high PANX1 expression might promote TAN infiltration in basal-like breast cancer TME." (PMID 35884429, 2022). "PANX1 has been found to be a poor prognostic factor in breast cancer, however, the role of PANX1 in breast cancer remains unknown." (PMID 35884429, 2022). "To further investigate the role of PANX1 expression in breast cancer, we analyzed TCGA-BRCA and METABRIC transcriptome data and confirmed that PANX1 was highly expressed in the basal-like subtype (TCGA-BRCA (n = 1083) and METABRIC (n = 1699) data, PAM50 algorithm)." (PMID 35884429, 2022). "PANX1 was shown to be highly expressed in the vast majority of tumors in the Oncomine database, including breast cancer, cervical cancer, colorectal cancer, esophageal cancer (ESCA), gastric cancer, head and neck cancer, kidney cancer, lymphoma, leukemia, lung cancer, pancreatic cancer, and sarcoma." (PMID 34796785, 2021). "Interestingly, therapeutic inhibition of PANX1 channels reduced breast cancer metastasis by increasing cell death within the microvasculature." (PMID 33257836, 2021). "In addition, gene set enrichment analysis (GSEA) was performed to find pathways enriched in breast cancer, based on PANX1 expression." (PMID 31817827, 2019). "In addition, the levels of PANX1 protein and mRNA were correlated in the different intrinsic breast cancer subtypes (R = 0.34, p = 0.004)." (PMID 31817827, 2019). "The elevated PANX1 expression in TCGA breast cancer tissues is correlated with clinical outcomes." (PMID 31817827, 2019). "Our results uncovered a role for PANX1 in breast cancer metastasis through EMT regulation." (PMID 31817827, 2019). "Overall, a pathway of PANX1 action could be envisaged to explain why PANX1 overexpression correlates with poor prognosis in breast cancer patients." (PMID 31817827, 2019). "High PANX1 expression was correlated with worse OS, RFS and DMFS in breast tumors from patients suggesting that PANX1 may act as a tumor facilitator in breast cancer." (PMID 27099931, 2016). "This study not only described a clear role for Panx1 in cancer metastasis, but also highlighted the possibility of using pharmacological inhibition of the Panx1 channel in mouse models with known channel blockers such as Carbenoxolone as a new therapeutic option to reduce breast cancer metastasis." (PMID 27229305, 2016).